IL6 (interleukin 6)
Diseases named in the same sentence as IL6 in open-access papers (continued):
Sharing a sentence is not in itself a finding about the gene and the disease.
cancer (continued). "In OSCC, IL1β is involved in the invasion and migration of cancer cells, while OSCC cells were reported to induce stromal cells to produce IL6, facilitating bone invasion by osteoclast formation." (PMID 36900301, 2023). "Prrx1-induced soluble factors included IL6, CSF, CCL5, and CXCL12, which promote both cancer progression and wound healing." (PMID 35589735, 2022). "Targeting principal components of IL-6 signalling (e.g., IL-6Rs, gp130, STAT3, NF-κB) is an intensively studied approach in preclinical cancer research." (PMID 36429126, 2022). "Mechanistically, IL-18-induced changes in the microbiota induce CC-chemokine ligand 5-driven inflammation, which accelerates epithelial cell proliferation through the regional activation of the IL-6/STAT3 pathway, eventually resulting in cancer formation." (PMID 36010693, 2022). "Oncology research has shown that multiple angiogenic proteins and their receptors show increased expression triggered by cancer-related hypoxia and inflammatory cytokines, such as tumor necrosis factor alpha (TNF-α) and interleukin-6 (IL-6)." (PMID 35741001, 2022). "S100A8 also significantly reduced protein levels of IL-6, IL-1β and IL-12β in BALF from mice with LLC cancers (p < 0.05)." (PMID 35655772, 2022). "Cytokine IL-6 is the main inflammatory mediator and stimulator of STAT3, which can block programmed cell death and facilitate cancer survival." (PMID 36371217, 2022). "Inflammatory mediators such as IL-1, IL-6, TNF-α, and IFN-γ are generated in cancer cachexia, resulting in increased energy expenditure, decreased appetite, and muscular atrophy." (PMID 35159388, 2022). "The results showed that IL-6, IL-10, and TNF concentrations in the saliva of patients with cancer were significantly higher in the post-index group than in the pre-index group and significantly positively correlated with OM grade." (PMID 35476641, 2022). "NETs induce gene expression of cancer stem cell marker CD24, and proinflammatory factors, such as IL1β, IL6, IL8, CXC motif chemokine receptor 1 (CXCR1), MMP2, MMP9 in cocultured luminal breast cancer cells." (PMID 35574410, 2022). "In NPC, IL‐6 activates signal transducer and activator of transcription 3 (STAT3) and promotes the proliferation, migration, and invasion of cancer cells." (PMID 36039641, 2022). "CAF-derived IL-6, SDF-1 and TGF-b1 promote cancer progression through induction of EMT, stemness and angiogenesis in a paracrine manner." (PMID 36359766, 2022). "In TME, to avoid T cell attack, cancer cells hijack inflammatory factors IFN-γ, TNF-α, IL-6-mediated inflammatory pathways to enhance PD-L1 expression." (PMID 36686771, 2022). "Recent strategies seek to block immunosuppressive ligands of major CAF signaling pathways such as IL-6, LIF, and TGF-β in order to suppress or kill cancer cells." (PMID 36010899, 2022). "Although the mean expression levels of IL6, CXCL8, IL10, and IL17A were higher in the cancer group than those in the control group, the difference was not statistically significant." (PMID 36501012, 2022). "IL6 was positively correlated with WZ3105 and MPS‐1‐IN‐1 in the cancer therapeutics response portal database." (PMID 35574984, 2022). "VAT exhibits a more pronounced secretion of IL-6 in comparison to SAT, and PPAT is suggested to be a valuable source of IL-6 in PCa patients, which correlates with cancer aggressiveness." (PMID 35406450, 2022). "IL‐6‐dependent STAT3 activation induces M2 polarization while inhibiting M1 activation, and this promotes cancer progression and reduces patient survival." (PMID 35356799, 2022). "Among them, IL-6, TNF-α, IL-1β, CRP, and albumin are the most investigated, but the correlation between them and cancer cachexia is elusive in humans." (PMID 36158184, 2022). "Catecholamines induced the expression and secretion of inflammatory mediators, such as interleukin 6 or 8 (IL6, IL8) from human cancer cells." (PMID 36074318, 2022).
cancer (continued). "The distribution of age, sex, cancer types, comorbidities, body weight, BMI, nutritional status, HGS, albumin, hsCRP, and IL-6 across the intervention groups were comparable at baseline." (PMID 35276977, 2022). "CAFs release high levels of IL-6 and TNF-α in an autocrine fashion upon STAT3 activation when co-cultured with cancer cells, promoting self-renewal and metastatic potential of cancer cells." (PMID 35443745, 2022). "For example, cisplatin triggers the expression of multiple cytokines including IL-6, CCL2, CCL5, CXCL8, BFGF, G-CSF, and VEGF in cancer cells or stromal cells of TME." (PMID 35784460, 2022). "Interleukin (IL6) and C‐C motif chemokine ligand 2 (CCL2), two cytokines secreted by CAF, play important role in cancer cell migration." (PMID 35978854, 2022). "Chronic IR is found in malignant tumors and presumed to contribute to cancer cachexia due to chronic exposure to proinflammatory cytokines, tumor necrosis factor (TNF)-α, IL-6, and insulin growth factor-binding protein, leading to IR." (PMID 35795140, 2022). "In contrast, depletion of IL6, IL8, or CCL2 by adding specific neutralizing antibodies to NPC cultures eliminated the cancer growth-promoting effect of Exo-Tx FibroCM, while treatment with isotype IgG control antibodies did not affect this effect." (PMID 35986369, 2022). "CAFs can promote the immunosuppression of cancer cells by secreting TGF-β, IL-6, CXCL12 and CCL2, thereby preventing cytotoxic T cell activity and recruiting immunosuppressive populations." (PMID 36185262, 2022). "Pro-inflammatory cytokines such as IL-1, IL-6, IL-17, and TNF-α promote proliferation and differentiation of cancer cells." (PMID 35252204, 2022). "Studies have demonstrated that downstream of STAT3, estrogen‐regulated zinc transporter LIV‐1, miR‐21, IL‐6, HIF, and VEGFR2 can repress E‐cadherin and modulate EMT in many cancers." (PMID 35356799, 2022). "Interleukin 6 (IL-6)/Signal Transducer and Activator of Transcription 3 (STAT3) signaling axis has been considered as an essential intrinsic pathway of cancer inflammation." (PMID 35813468, 2022). "In various types of cancer, findings between NNMT and immunostimulator gene expression showed a high connection (p < 0.05), including TNFSF13B, TNFRSF8, TNFSF14, IL6, IL2RA, CD80, CD27, and CD86." (PMID 36386816, 2022). "Several representative cancer pathways were tightly related to AC010973.2, including E2F targets, IL6-JAK-STAT3 signaling, apoptosis signaling, hypoxia signaling, and fatty acid metabolism." (PMID 35277527, 2022). "The oncogenic activity of inflammatory signaling factors such as IL-6 and OSM has been classically attributed to cell-intrinsic mechanisms within the cancer cell." (PMID 35192545, 2022). "MIF is an upstream modulator of IL-6 and the IL-6/JAK/STAT pathway and has a vital impact on the growth and development of many human cancers." (PMID 36042480, 2022). "Processes significantly influenced the development of cancer, including MYC targets V2, DNA repair, IL-6/JAK/STAT3 signaling, and immune response." (PMID 36226251, 2022). "Consistent with this, our study confirmed the upregulation of IL‐6, LIF and IL‐11 in iCAF after the activation of PSCs by CM from cancer cells." (PMID 36282889, 2022). "The hyperactivation of IL-6 and IL-1-dependent STAT3 signaling is correlated with poor patient prognosis and occurs in most human cancers including breast cancer." (PMID 35053592, 2022). "Considering cancer immunosuppressive mechanisms, indoleamine-2,3-dioxygenase (IDO) enzyme and interleukin-6 (IL-6) stand out in HPV-related tumors." (PMID 36405719, 2022). "LIF belongs to the interleukin-6 (IL-6) family of cytokines, promotes EMT, and is envisioned as a potential therapeutic target in many cancers." (PMID 35847866, 2022).
cancer (continued). "MDSCs in TME released IL-6 to constantly activate STAT3 in cancer cells, which conferred invasive potential to cancer cells, induced epithelial mesenchymal transition (EMT) of cancer cells, and enhanced cancer cell stemness." (PMID 35267547, 2022). "The study concluded that silibinin had chemoprotective potential via the IL-6/STAT3 pathway, giving it dual beneficial activity in cancer and inflammation, both of which are present in colitis-associated cancer." (PMID 36145523, 2022). "Furthermore, increased IL-6 may lead to a variety of inflammatory diseases and malignant tumors." (PMID 36364151, 2022). "Mechanistically, leptin binds its receptor OB-R in CSCs by promoting activation of the JAK/STAT3, c-Jun, and Akt pathways, thus inducing the transcription of IL-6, TGF-β, and MMP, which drive cancer cell proliferation and invasion." (PMID 35625629, 2022). "MTCAF-derived ICAM-1 has double roles: It not only regulates the growth and migration of MTCAFs by mediating the expression of IL6 and IL8 in MTCAFs but also can promote the proliferation and invasion of cancer cells." (PMID 36016615, 2022). "Overall, these findings will be important to inform the development of therapeutic strategies to improve outcomes for patients with this deadly cancer and other diseases where the IRF9-mediated production of IL-6 can be therapeutically modulated." (PMID 35205671, 2022). "KRAS influences the inflammatory milieu of cancer by activating the MAPK and PI3K signaling pathways, which results in the release of additional IL-6/IL-8 cytokines and cancer cell proliferation." (PMID 36776374, 2022). "From the outcome of the present study, it was found that physical exercise can reduce cancer incidence by improving immunity markers such as TNF-α, IL-6, IL-10, and NK cells." (PMID 35935260, 2022). "In both cancers, gastric and esophagus, IL-32 upregulation was coupregulated with proinflammatory cytokines such as TNF-α, IL-1β, and IL-6, suggesting its induction via NF-κB and STAT3 signaling pathways was linked to poor-prognosis cases." (PMID 35281008, 2022). "Serum concentrations of IL–6 and CRP are known to be positively correlated with each other, and recent evidence suggests that IL–6 also affects the rate of cancer progression." (PMID 34980029, 2022). "The result revealed that the expressions of NOD2, CASP1, IL6, and NLRP6 were negatively correlated with some or most drugs, while IL6 was also positively correlated with WZ3105 and MPS‐1‐IN‐1 in the cancer therapeutics response portal database." (PMID 35574984, 2022). "During cancer cachexia, cytokines such as TNF‐α and IL‐6 enter the central nervous system and promote the wasting of surrounding tissues, such as muscles through the hypothalamus–pituitary–adrenal and hypothalamus–pituitary–gonad axes." (PMID 36105371, 2022). "In the experiment of colorectal cancer, TAMs–derived IL–6 activated the JAK2/STAT3 pathway and inhibited the tumor suppressor Mir–506–3p in cancer cells." (PMID 36059616, 2022). "Activated osteoblasts release IL-6, monocyte chemoattractant protein-1 (MCP-1), VEGF-A, and macrophage inflammatory protein-2 (MIP-2), which trigger the development of metastatic cancer cells and communication with bone stromal cells." (PMID 35203510, 2022). "Particularly, CAFs secrete SDF-1, which stimulate cancer cell growth via CXCR-4 receptor, but also different factors such as TGF-β and VEGF, IL-6, mediating stemness and EMT." (PMID 35682974, 2022).
cancer (continued). "Resveratrol nanoparticles can inhibit the growth, proliferation and migration of cancer stem like cells by inducing M1-like macrophages producing inflammatory cytokines such as TNF-α, IL-6 and IL-1β." (PMID 36439106, 2022). "The abnormal expression of targets (IL6, MAPK1, PPARG, PTGS2, and MAPK3) leads to cell proliferation and a variety of cancer types." (PMID 35992697, 2022). "This demonstrates a new proof in inflammation-cancer transition of CRC involving CypB-supported STAT3 activation and their interaction with downstream ncRNAs induced by IL-6 cascades." (PMID 36266267, 2022). "Inflammatory cytokines such as IL-6, CCL-1, MCP-1, and VEGF play a vital role in cancer progression and metastasis." (PMID 35222023, 2022). "Proinflammatory cytokines such as TNF-α, IL-6, IL-1β, TGF-β, and IFN-γ modulate PD-L1 expression in both cancer and stromal cells." (PMID 35326493, 2022). "IL-6/JAK/STAT3 pathway is predicted to be activated in TAb2 tumors, which is often hyperactivated in various types of cancer that correlates with poor prognosis." (PMID 35366939, 2022). "Inhibited FOXO1 phosphorylation retarded its regulatory activities in maintaining cancer stemness including ALDH1 and IL6." (PMID 35637961, 2022). "Like IL-6 and TNF-α, it is involved in cancer stromal activation, immune escape, angiogenesis, migration, and differentiation of many cell types and inhibition of apoptotic pathways." (PMID 36289922, 2022). "With cytokines such as the IL-1β, IL-6, and TNF all having pro-angiogenic properties, it is clear that inflammation and angiogenesis are related to cancer." (PMID 35626056, 2022). "Using a cancer tissue‐originated spheroid experiment, CAF‐secreted IL‐6 and TGF‐β contribute to tumor progression, the acquisition of stemness and drug resistance." (PMID 35603909, 2022). "In human colorectal cancer, CAFs promoted cancer proliferation, EMT and metastasis by secreting pro-inflammatory factors, such as IL-6, IL-8 and exosomal miRNA-92a-3p to activate Wnt/β-catenin pathway as well as inhibit mitochondrial apoptosis." (PMID 36185262, 2022). "Hence, again, targeting the IL-6/STAT3 axis might be a promising outcome in cancers." (PMID 36091805, 2022). "While JAK inhibition remains heavily studied in multiple cancers, the FDA has administered safety warnings against JAK inhibitors underscoring the need to investigate additional approaches to target the IL-6/JAK/STAT3 pathway." (PMID 35371975, 2022). "variant Indonesia and Philippines treatment groups had lower expression of IL-6, STAT3 and vimentin that imply a decrease in cell cancer survival." (PMID 37829248, 2022). "IL-6/JAK2/STAT3 signaling pathway plays a crucial role in the development and progression of cancer." (PMID 36591515, 2022). "In the early stages of cancer development after PAH exposure, CYP1A1, HO-1, NQO-1, and IL-6 were identified as exposure biomarkers." (PMID 36056034, 2022). "Meanwhile, there were pieces of evidences that the inflammation induced by IL-6 and IL-1β was through the MAPKs, NF-ΚB, and STAT3 pathways in many cancers." (PMID 35280511, 2022). "Conversely, blockade of IL-6 abrogated the induction of EMT- and CSC-related alterations in S. mutans -infected cancer cells." (PMID 36186905, 2022). "Although several publications have indicated an association between fatigue and systemic cytokines such as IL-1β, IL-2, IL-6, IP-10, and TNF in cancer patients, the results are conflicting." (PMID 36350483, 2022). "At the promotion stage, inflammatory cytokines (notably TNF, IL-1β and IL-6) induce NF-κB and STAT3 transcription factors in cancer cells, which activate genes controlling cell survival, proliferation and growth." (PMID 35406394, 2022). "In the TME, cancer cells induce expression of MHC-II, CD40, CD80, and CD86 on DCs, together with the release of inflammatory cytokines like IL-12, type I IFN, IL-1β, IL-6 and tumor necrosis factor (TNF)." (PMID 35267487, 2022).
cancer (continued). "Our previous work has described the correlation between elevated levels of serum cytokines IL-6 and TNF-α in the cancer progression and grading changes in localized PCa, showing the great potentiality of cytokines to impact cancer diagnostics." (PMID 36059480, 2022). "IL‐17 cytokines family can activate the production of NF‐κB, IL8, IL6, TNF‐α, and IL1b, contributing to various inflammatory diseases and cancers." (PMID 35373393, 2022). "Constitutively active IL-6/JAK/STAT3 signaling drives cancer cell proliferation and invasiveness while suppressing apoptosis, and STAT3 enhances IL-6 signaling to promote a vicious inflammatory loop." (PMID 35371975, 2022). "Metformin strengthens the anti-inflammatory effect of 5-aminosalicylic acid (5-ASA) by suppressing the expression of IL-1β, IL6, COX-2, TNF-α, and TNF receptors in cancer cells." (PMID 35565252, 2022). "Cancer cells produce pro-inflammatory cytokines such as IL-6 and TNF-α, which produce inflammatory reactions between cancer cells and their hosts." (PMID 35057531, 2022). "Serum levels of cytokines, such as TNFα, IL-1β, IL-6, IL-10, and IL-2R, are increased in SIRS, and among these, IL-6 in particular is known to be involved in cancer progression and C-reactive protein synthesis in the liver." (PMID 35203589, 2022). "The main types of copy number variations of pyroptosis genes in pan-cancer were heterozygous amplifications and deletions, among which the CNVs of CHMP4B, CHMP4C, and IL6 in most tumors were heterozygous amplifications." (PMID 36090967, 2022). "IL-6 is often identified as a major mediator of inflammation, and IL-6 production by macrophages has been shown to drive CRS in cancer immunotherapies." (PMID 35512020, 2022). "Dual treatment of MSL TNBC cell lines with docetaxel and an IL-6 neutralizing antibody led to a significant reduction in phosphorylation of STAT3, a potent transcription factor for cancer proliferation." (PMID 35260569, 2022). "Our study found that in addition to regulating pathways involved in cancer progression, TMEM59L was also involved in immune regulatory pathways such as IL6-JAK-STAT3, IL2-STAT5, and TGF-β signaling." (PMID 36618425, 2022). "Functionally, the IL-6/JAK/STAT3 signaling axis promotes proliferation, angiogenesis, EMT, and the cancer stem cell (CSC) subpopulation, while concurrently suppressing the antitumor immune response." (PMID 35371975, 2022). "Although systemic inflammation is not considered in the current classification as a parameter for diagnosing cancer cachexia, several authors have considered the measurement of inflammatory markers, such as CRP and IL-6, at the blood level." (PMID 36072935, 2022). "ING5 suppresses aggressive phenotypes of various cancer cells via EGFR/PI3K/Akt, IL-6/STAT3, Akt/NF-κB/NF-κB/MMP-9 or IL-6/CXCL12 pathway." (PMID 36425530, 2022). "IL-6 plays a crucial role in maintaining normal cell growth through STAT3 activation, and its aberrant activation results in the proliferation of cancer cells." (PMID 35956786, 2022). "In cancer, NLRX1 has been shown to downregulate key cytokines that are important in cancer progression, such as tumor necrosis factor (TNF) and interleukin (IL)-6." (PMID 34697412, 2022). "Nociceptors are capable of detecting different forms of noxious stimuli (ATP, IL1, IL6, NGF, VEGF, TNFa, protons) that are secreted by cancer cells and other components of the TME." (PMID 35663547, 2022). "This is because macrophages produce IL6 and IL10, promoting cancer proliferation and inhibiting cytotoxic T cell proliferation." (PMID 35629230, 2022).